GABRA5 (gamma-aminobutyric acid type A receptor subunit alpha5)
Description:
Alpha subunit of the heteropentameric ligand-gated chloride channel gated by gamma-aminobutyric acid (GABA), a major inhibitory neurotransmitter in the brain. GABA-gated chloride channels, also named GABA(A) receptors (GABAAR), consist of five subunits arranged around a central pore and contain GABA active binding site(s) located at the alpha and beta subunit interface(s). When activated by GABA, GABAARs selectively allow the flow of chloride anions across the cell membrane down their electrochemical gradient. GABAARs containing alpha-5/GABRA5 subunits are mainly extrasynaptic and contribute to the tonic GABAergic inhibition in the hippocampus (By similarity). Extrasynaptic alpha-5-containing GABAARs in CA1 pyramidal neurons play a role in learning and memory processes (By similarity).
Synonyms: DEE79; EIEE79
Tractability: Small molecule: an approved drug acts on it; a structure with a bound ligand is known; a high-quality ligand is known; it belongs to a druggable protein family. Antibody: UniProt places it where antibodies can reach, with high confidence; its Gene Ontology location is reachable by antibodies, with high confidence; UniProt predicts a signal peptide or a membrane-spanning region; the Human Protein Atlas places it where antibodies can reach. PROTAC: UniProt records ubiquitination sites on it; ubiquitination databases record sites on it; its protein half-life has been measured; a small molecule that binds it is known.
Target class: Ion channel; GABA-A receptor; Ligand-gated ion channel
Chemical probes: BI-1030 (high quality), CHEMBL35571, RO4938581 (high quality)
Safety:
Unwanted effects reported when the protein is acted on. In parentheses: how it was acted on, where the effect was seen, and who reports it.
ataxia (activation, acute dosing; central nervous system, cardiovascular; source: Lynch et al. (2017))
convulsions (inhibition, acute dosing; central nervous system, cardiovascular; source: Lynch et al. (2017))
decreased anxiety (activation, acute dosing; central nervous system, cardiovascular; source: Lynch et al. (2017))
decreased blood pressure (activation, acute dosing; central nervous system, cardiovascular; source: Lynch et al. (2017))
decreased body temperature (activation, acute dosing; central nervous system, cardiovascular; source: Lynch et al. (2017))
decreased cardiac contractility (activation, acute dosing; central nervous system, cardiovascular; source: Lynch et al. (2017))
decreased convulsions (activation, acute dosing; central nervous system, cardiovascular; source: Lynch et al. (2017))
decreased locomotor activity (activation, acute dosing; central nervous system, cardiovascular; source: Lynch et al. (2017))
decreased memory (activation, acute dosing; central nervous system, cardiovascular; source: Lynch et al. (2017))
decreased pain (activation, acute dosing; central nervous system, cardiovascular; source: Lynch et al. (2017))
decreased sleep (inhibition, acute dosing; central nervous system, cardiovascular; source: Lynch et al. (2017))
drug abuse/dependence (activation, acute dosing; central nervous system, cardiovascular; source: Lynch et al. (2017))
increased cardiac output (activation, acute dosing; central nervous system, cardiovascular; source: Lynch et al. (2017))
increased eating (activation, acute dosing; central nervous system, cardiovascular; source: Lynch et al. (2017))
increased respiratory rate (activation, acute dosing; central nervous system, cardiovascular; source: Lynch et al. (2017))
increased sleep (activation, acute dosing; central nervous system, cardiovascular; source: Lynch et al. (2017))
muscle relaxation (activation, acute dosing; central nervous system, cardiovascular; source: Lynch et al. (2017))
Occurrence, Epileptic seizure (brain; source: AOP-Wiki)
Gene: Protein-coding gene on chromosome 15 (26,866,911 to 26,949,208, forward strand). Ensembl gene ENSG00000186297.
Subcellular location: Postsynaptic cell membrane; Cell membrane
Subcellular location (Human Protein Atlas): Plasma membrane; Actin filaments; Cytosol; Nucleoplasm
Pathways (Reactome):
Neuronal System: GABA receptor activation
Gene Ontology:
Molecular function: ligand-gated monoatomic ion channel activity involved in regulation of presynaptic membrane potential; GABA-A receptor activity; GABA-gated chloride ion channel activity; signaling receptor activity; extracellular ligand-gated monoatomic ion channel activity; GABA receptor binding; monoatomic ion channel activity; transmembrane signaling receptor activity; transmitter-gated monoatomic ion channel activity involved in regulation of postsynaptic membrane potential
Biological process: chloride transmembrane transport; gamma-aminobutyric acid signaling pathway; inhibitory synapse assembly; signal transduction; synaptic transmission, GABAergic; chemical synaptic transmission; chloride transport; cochlea development; inner ear receptor cell development; innervation; monoatomic ion transmembrane transport; monoatomic ion transport; neuron development; regulation of postsynaptic membrane potential; regulation of presynaptic membrane potential
Cellular component: GABA-A receptor complex; plasma membrane; postsynaptic membrane; dendrite membrane; postsynapse; cell body; dendrite; GABA-ergic synapse; membrane; neuronal cell body membrane; postsynaptic specialization membrane; presynaptic membrane; receptor complex
Genetic constraint (gnomAD): Loss-of-function variants: 16 observed, 43.42 expected, observed/expected ratio (o/e) 0.37, 90% interval 0.25 to 0.56. The upper end of that interval is the gene's LOEUF score, 0.56, which puts it in group 2 of 6, group 1 being the genes least tolerant of losing a copy. Missense variants: 341 observed, 550.7 expected, observed/expected ratio (o/e) 0.62, 90% interval 0.57 to 0.68. Synonymous variants: 226 observed, 215.77 expected, observed/expected ratio (o/e) 1.05, 90% interval 0.94 to 1.17.
Homologues: Orthologues: chimpanzee GABRA5 (100% identical), macaque GABRA5 (99% identical), rabbit GABRA5 (98% identical), dog GABRA5 (97% identical), pig GABRA5 (97% identical), guinea pig GABRA5 (96% identical), mouse Gabra5 (95% identical), rat Gabra5 (95% identical), tropical clawed frog gabra5 (83% identical), zebrafish gabra5 (76% identical). Paralogues in human: GABRA2 (71% identical), GABRA3 (70% identical), GABRA1 (69% identical), GABRA4 (55% identical), GABRA6 (55% identical), GABRG1 (43% identical), GABRG2 (42% identical), GABRG3 (42% identical), GABRE (34% identical), GLRA2 (34% identical), GLRA1 (33% identical), GABRB1 (33% identical), and 33 more.